MGST1 (microsomal glutathione S-transferase 1)
Diseases named in the same sentence as MGST1 in open-access papers (continued):
Sharing a sentence is not in itself a finding about the gene and the disease.
lymphoma (2 papers, 2016 to 2025). A malignant (clonal) proliferation of B- lymphocytes or T- lymphocytes which involves the lymph nodes, bone marrow and/or extranodal sites. "In addition, we validate findings suggesting that MGST1 is differentially expressed between high and low abundance culture initiating cells in multiple myeloma and that microRNA-127 is differentially expressed between testicular and nodal lymphomas." (PMID 27067838, 2016).
neuroblastoma (2 papers, 2018 to 2020). Neuroblastoma (NB) is the most common solid, extracranial childhood tumor. "It has been observed that MGST1 expression was very low in neuroblastomas and neuroblastoma cell line." (PMID 30670947, 2018). "Surprisingly MGST1 mRNA or protein cannot be detected in neuroblastoma cells or tissues." (PMID 33014847, 2020).
non-small cell lung carcinoma (2 papers, 2017 to 2023). A group of at least three distinct histological types of lung cancer, including non-small cell squamous cell carcinoma, adenocarcinoma, and large cell carcinoma. "The principal association between MGST1 and lung diseases includes different types of cancer, such as adenocarcinoma or non-small cell lung cancer." (PMID 36825998, 2023). "In the non-small cell lung cancer model the following 5 DEPs were found to be involved in the GSH metabolism pathway (G6PD, PRDX2, IDH1, MGST1 and 6PGD), 4 DEPs in the PPP pathway (G6PD, TALDO1, TKT and 6PGD) and 1 DEP involved in the glycolysis pathway (ALDH3A1)." (PMID 28303926, 2017).
osteoarthritis (2 papers, 2022 to 2023). A noninflammatory degenerative joint disease occurring chiefly in older persons, characterized by degeneration of the articular cartilage, hypertrophy of bone at the margins and changes in the synovial membrane. "MGST-1 has previously been identified as a hub gene in the pathological process of osteoarthritis, and the mRNA was shown to be highly expressed in human iAF cells from degenerating IVDs." (PMID 35409356, 2022). "Although there is no clear enrichment in the UMAP plot, MGST1 has previously been identified as a hub gene in the pathological process of osteoarthritis, and the mRNA has been shown to be highly expressed in human iAF cells from degenerating IVDs." (PMID 35409356, 2022).
uterine corpus endometrial carcinoma (2 papers, 2022 to 2024). A endometrial carcinoma (disease) that involves the body of uterus. "MGST1 can be used as a potential prognostic indicator and immunotherapy target based on iron ptosis in uterine corpus endometrial carcinoma." (PMID 39711549, 2024).
acute pancreatitis (1 paper, 2025). An acute inflammatory process that leads to necrosis of the pancreatic parenchyma. "Under TCS stimulation, MGST1 expression was significantly elevated in the supernatant of ductal cells, further suggesting that MGST1 can be released from ductal cells into the periphery during the onset of acute pancreatitis." (PMID 40076525, 2025). "In the in vitro experiments, we discovered for the first time that ferroptosis occurs in pancreatic duct cells during acute pancreatitis, and that MGST1 is significantly upregulated in duct cells, where it plays a crucial role in negatively regulating ferroptosis via the ACSL4/GPX4 axis." (PMID 40076525, 2025).
cataract (1 paper, 2013). Partial or complete opacity of the crystalline lens of one or both eyes that decreases visual acuity and eventually results in blindness. "The mRNA level of MGST1 was about threefold higher in the PEX and cataract samples (median=4,439 mRNA copies/μg of total RNA) than in the control cataract group samples (median=1,243 mRNA copies/μg of total RNA)." (PMID 23805041, 2013). "Therefore, the present study focused on quantitative relationships of SOD2, ALDH1A1, and MGST1 messenger ribonucleic acid (mRNA) levels between patients presenting with cataracts with and without PEX." (PMID 23805041, 2013).
cholestasis (1 paper, 2021). Impairment of the bile flow caused by obstruction within the liver, or outside the liver in the bile duct system. "Cancer and/or non-alcoholicfatty liver disease-related cirrhosis showed larger deteriorationin levels of CYP3A4, 2C8, 2E1, 1A6, UGT2B4/7, CES1, FMO3/5, EPHX1,MGST1/3, BSEP, and OATP2B1 than the cholestasis set." (PMID 34428046, 2021).
Cirrhosis (1 paper, 2021). A chronic disorder of the liver in which liver tissue becomes scarred and is partially replaced by regenerative nodules and fibrotic tissue resulting in loss of liver function. "Targets affected only by NAFLD-associated cirrhosis were CYP2C8,MGST1, MGST3, UGT2B4, FMO5, and BSEP, while targets that showed asignificant reduction only with cancer-associated cirrhosis were CYP2E1and UGT1A6." (PMID 34428046, 2021). "Wealso quantified nine non-CYP and non-UGT metabolizing enzymes, residentin the endoplasmic reticulum, in all stages of cirrhosis severity,of which, MGST1, MGST3, and FMO5 are reported for the first time incirrhosis." (PMID 34428046, 2021). "For the moderate cirrhosis group, some targets showeda statistically significant reduction from the control, by 40 to 50%,such as MGST1, MDR1, MRP3, OCT3, and ATP1A1." (PMID 34428046, 2021).
congenital heart defects (1 paper, 2021). "Furthermore, genetic variants of SHMT1, BHMT, MGST1, MGMT, MTHFS, GNMT, and TRDMT1 were associated with an increased risk of congenital heart defects after prenatal antidepressant exposure." (PMID 33981330, 2021).
diabetic cardiomyopathy (1 paper, 2024). Diabetic cardiomyopathy is a disorder of the heart muscle in people with diabetes. "At present, there are few studies on MGST1 in heart disease, and no study has been reported in diabetic cardiomyopathy." (PMID 39711549, 2024).
diabetic retinopathy (1 paper, 2025). "Our findings reveal a dual-stress pattern in diabetic retinopathy: mitochondrial compromise marked by IDH2 and MGST1 suppression, and a sulfur-driven antioxidant defense through Nrf2 activation." (PMID 41334440, 2025).
head and neck carcinoma (1 paper, 2014). A carcinoma that arises from the head and neck region. "Of 138 genes identified as being associated with SF2, only 2 (1.4%) were congruent between the cervix and head and neck carcinoma cell lines (MGST1 and TFPI), and these did not partition the published NCI-60 cell lines based on SF2." (PMID 24466029, 2014).
heart defects (1 paper, 2023). "Prior work in our lab identified rs7294985 as an MGST1 polymorphism that influences the risk of heart defects among infants with prenatal exposure to selective serotonin reuptake inhibitors (SSRIs)." (PMID 36672920, 2023).
inflammatory bowel disease (1 paper, 2024). A spectrum of small and large bowel inflammatory diseases of unknown etiology. "Upregulation of MGST1 has been implicated in initiating changes related to oxidative stress resulting from inflammatory bowel disease (IBD) pathogenesis in rat models." (PMID 39199837, 2024).
ischemic cardiomyopathy (1 paper, 2025). Ischemic cardiomyopathy is a cardiomyopathy in which a weakness in the muscle of the heart due to inadequate oxygen delivery to the myocardium with coronary artery disease being the most common cause. "Bulk RNA-seq data from the GSE116250 cohort revealed significant overlap between ischemic cardiomyopathy (ICM)-associated differentially expressed genes (DEGs) and FB3-specific markers (THBS4, NTM, NRK, COL14 A1 upregulated; MGST1 downregulated)." (PMID 40447667, 2025).
lymph node metastasis (1 paper, 2025). "We demonstrated that EpCAM and MGST1 were abundantly expressed in LSCC, particularly in cases with lymph node metastasis." (PMID 40778224, 2025). "In addition, it was noted that, unlike EpCAM, the differential expression of MGST1 was only observed in cases with lymph node metastasis compared to cases without metastasis." (PMID 40778224, 2025).
Obesity (1 paper, 2018). Accumulation of substantial excess body fat. "This study is a first step towards the identification of biomarkers for early-stage obesity (GSTT1, GSTT3, GSTM1, MGST1, MGST3, SOD2, CAT) and glucose load (CRYM) in cattle." (PMID 30235219, 2018).
osteosarcoma (1 paper, 2025). A usually aggressive malignant bone-forming mesenchymal neoplasm, predominantly affecting adolescents and young adults. "A subsequent clinical study, which performed an expression profile analysis on genes regulating cell proliferation, metastasis, and DR in canine osteosarcoma patients, found that MGST1 and HMGB1 genes were overexpressed in dogs with MDR as in humans with other tumors." (PMID 40563676, 2025).
Pneumocystis infection (1 paper, 2010). "Among the genes that were affected by dexamethasone and further affected by Pneumocystis infection, Mgst1 and Hspa1b genes were down-regulated, while Cd14, Irf8, Il1b, Cxcl13, Cxcr4, Fn1, Irf1, Cd74, S100a9, and Spp1 genes were up-regulated in all four groups." (PMID 20377877, 2010).
Vertigo (1 paper, 2022). An abnormal sensation of spinning while the body is actually stationary. "In conclusion, we identified three high-confidence genes (RAB3B, MTERFD2, and MGST1) showed proteome-wide significant associations in the human brain with vertigo in two independent brain proteomes, strongly highlighting the underlying pathogenesis of these proteins in vertigo." (PMID 36519156, 2022). "Importantly, three common vertigo risk genes showed proteome-wide significant signals in both discovery and replication stages, including MTERFD2 (PBanner = 0.045, PROSMAP = 0.031), MGST1 (PBanner = 0.014, PROSMAP = 0.018), and RAB3B (PBanner = 0.045, PROSMAP = 0.035)." (PMID 36519156, 2022). "They provide novel genes (MTERFD2, MGST1, and RAB3B) into the pathogenesis of vertigo, and highlight promising chemicals for further therapeutics research." (PMID 36519156, 2022).
cancer (29 papers, 2010 to 2025). A tumor composed of atypical neoplastic, often pleomorphic cells that invade other tissues. "To corroborate decreased MGST1 expression conferred the susceptibility of cancer to ferroptosis, we also performed IHC with antibody specific for 4-HNE (a lipid peroxidation marker) to examine the ferroptosis level in xenografts." (PMID 39501138, 2024). "Furthermore, we detected MGST1 expression and infiltrated immune cells such as NK cells and cancer‐associated fibroblasts via the TIMER and GEPIA databases." (PMID 35218676, 2022). "MGST1 is overexpressed in various cancers and associated with drug resistance." (PMID 33014847, 2020). "MGST1 polymorphisms may also influence an individual’s susceptibility to specific cancers." (PMID 38169383, 2024). "MGST1, which possesses glutathione transferase and peroxidase activities, plays a multifaceted role in tumorigenesis, particularly by influencing cancer cell survival and proliferation through antioxidant, anti-apoptotic, and drug-resistance mechanisms." (PMID 41315466, 2025). "More importantly, the involvement of high expression of MGST1 in drug resistance of cancer cells has been confirmed." (PMID 39850123, 2025). "Aberrant high expression of MGST1 has been reported in multiple types of cancers, including lung cancer." (PMID 39850123, 2025). "GATM and MGST1 have been identified as novel biomarkers implicated in the progression of both HCM and cancer." (PMID 39160643, 2024). "In these cancer cells, exposure to ferroptosis inducers leads to a reduction in MGST1 expression at both protein and mRNA levels." (PMID 38562143, 2024). "Functionally, GATM and MGST1 are likely involved in xenobiotic metabolism and epithelial mesenchymal transition in a wide range of cancer types." (PMID 39160643, 2024). "As MGST1 inhibition is a valuable way to overcome ferroptosis resistance in vitro and in vivo, this approach can represent an experimental basis for MGST1-mediated ferroptosis resistance, exploiting it as a potential target for cancer treatment." (PMID 37132605, 2024). "The results obviously showed that MGST1 was upregulated in the majority of cancers as well as in UCEC." (PMID 35218676, 2022). "Further analysis showed that all of these dysregulated proteins had cancer-related associations, such as PDIA5, DEF6, MZB1, TXNDC5, YARS2, MGST1, and PIH1D1." (PMID 35958927, 2022). "First, genomic analyses of MGST1 revealed different levels of MGST1 across cancers by excavating TCGA, GEO and Human Protein Atlas data." (PMID 35218676, 2022). "MGST1 plays a critical role in inflammation, is overexpressed in cancer, and correlates with drug resistance." (PMID 36135194, 2022). "Taken together, these in silico analyses may provide guidance for further research on the regulatory mechanisms of EpCAM and MGST1 in cancers." (PMID 40778224, 2025). "MGST1 has been reported to exert an inhibitory effect on ferroptosis in various cancer cells." (PMID 39850123, 2025). "Dysregulation of MGST1 has been found in different human cancers." (PMID 39850123, 2025). "Additionally, ADNP2, PCDH11X, and MGST1 detected to be highly expressed in the transformed HGG model have been associated with EMT and treatment resistance in various cancer types." (PMID 39256867, 2024). "According to these findings, MGST1 has a significant impact on cancer cells and could be a promising target for therapy." (PMID 39501138, 2024). "Multiple studies have shown that MGST1 is closely related to the ferroptosis in cancer disease." (PMID 39711549, 2024). "DNA methylation might also impact the expression levels of GATM and MGST1 because four methyltransferases were significantly correlated with their expression among cancers." (PMID 39160643, 2024). "Furthermore, MGST1 exerts inhibitory effects on the process of ferroptosis in cancer cells by interacting with ALOX5, or its lipid peroxidase activities." (PMID 38169383, 2024).
cancer (continued). "Similarly, existing research highlights MGST1 as a critical player in various cancers, reinforcing its potential as a therapeutic target." (PMID 39160643, 2024). "In addition, we revealed that GATM and MGST1 played significant roles in cancer by affecting several classic cancer hallmarks." (PMID 39160643, 2024). "Recent studies propose that MGST1 plays a unique role in inhibiting ferroptosis in cancer cells and may be a potential therapeutic target." (PMID 35218676, 2022). "MGST1 (microsomal glutathione S‐transferase 1) involves in the regulation of oxidative stress and plays a key role in inhibiting iron‐mediated cell death in cancer cells." (PMID 35218676, 2022). "The transcription levels of MGST1 were first analysed in pan‐cancers." (PMID 35218676, 2022). "Three more SNPs (Gga_rs14524377, Gga_rs13878108 and GGaluGA217414) having association with IMFBr were in the proximity of protein tyrosine kinase (TYRO3), microsomal glutathione S-transferase 1 (MGST1) and nucleoside-triphosphatase, cancer-related (NTPCR) genes, on GGA5, GGA1 and GGA3, respectively." (PMID 23834466, 2013). "Notably, genes such as TTC3, TMSB4X, MGST1, DNAJC3, and P4HB are closely linked to cancer cell proliferation and migration and may serve as key regulators of CC progression." (PMID 41315466, 2025). "Thus, we also investigated the role of GATM and MGST1 among cancers." (PMID 39160643, 2024). "According to previous works and the novel findings in our work, we hypothesized that high GATM and MGST1 expression in HCM might promote cancer progression through xenobiotic metabolism and immune‐related signatures, and the detailed cause‐result relation needs to be further investigated." (PMID 39160643, 2024). "According to the results, MGST1, GPX3, SP1, TXNRD1, MAPK14, and SOD1 presented with CNV gains among various types of cancers." (PMID 34721758, 2021).
tumor (27 papers, 2009 to 2025). "Our results reveal the association between ferroptosis and tumour‐infiltrating immune cells with dysregulated MGST1, which has the potential to be designed for ferroptosis inducer, and provide promising combinational therapy strategies in the future." (PMID 35218676, 2022). "The levels of various immune cells associated with the expression of MGST1 and tumour purity in UCEC are outlined." (PMID 35218676, 2022). "Both APEX1 and NOP2 are recognized regulators of tumor metastasis, suggesting a potential mechanism wherein the lymphatic metastasis associated with high MGST1 could be attributed to the overexpression of either APEX1 or NOP2." (PMID 40778224, 2025). "High expression of MGST1 was also found to be associated with the high frequency of tumor invasion." (PMID 35847989, 2022). "Moreover, MGST1 is closely associated with tumour cell epithelial–mesenchymal transformation, viability, migration and invasion." (PMID 35218676, 2022). "As determined by immunohistochemical staining, Ki-67 expression was decreased, while p-H2A.X expression was increased in DDP-treated tumor tissues, and these changes were further reinforced when MGST1 was silenced." (PMID 39850123, 2025). "Genes specifically upregulated in the high mRNAsi group included MKI67, MGST1, and ALOX5AP, which are associated with lipid metabolism, endoplasmic reticulum stress, and tumor progression." (PMID 40963856, 2025). "The expression level of MGST1 was upregulated in the tumor group (n = 179) compared with that in the normal group (n = 171)." (PMID 39501138, 2024). "In order to explore the anti-tumor effect of MGST1 knockdown, we utilized LF3 and PKF-118-310, two antagonist of the β-catenin/Tcf4 complex that possesses anti-tumor properties." (PMID 39501138, 2024). "Knockdown of MGST1 in MRTX1133-resistant PDAC cells increased the anti-tumor activity of MRTX1133 in vivo." (PMID 39501138, 2024). "Treatment with 1 mg/kg MRTX1133 results in significant suppressing of tumour growth and the tumour weight in MGST1 KO group." (PMID 39501138, 2024). "To better explore the role of MGST1 in MRTX1133-resistant PDAC tumors, we implanted 3 × 105 MGST1 knockout (MGST1 KO) cells subcutaneously into nude mice to induce tumor growth." (PMID 39501138, 2024). "Just to illustrate the differences in protein expression between tumor and normal tissues, we generated a histopathological atlas comparing MGST1 immunohistochemistry results in both tissue types." (PMID 39594421, 2024). "Although recent studies provided further evidence for these and other proteins, such as MGST1, to be involved in tumor dissemination, these proteins appeared to share an ability to regulate the formation of metastases in various cancers." (PMID 36428591, 2022). "Overexpression of MGST1 in tumor tissue can inhibit tumor cell apoptosis by inhibiting apoptosis-related signaling." (PMID 36566175, 2022). "Our results show that MGST1 is overexpressed in UCEC tumours and that overexpression of MGST1 correlates with reduced survival time." (PMID 35218676, 2022). "Elevated MGST1 expression is related to tumour development and poor prognosis, as well as dysregulated infiltration of immune cells in UCEC, which can be a potential prognostic indicator and ferroptosis‐based immunotherapy target." (PMID 35218676, 2022). "Our analysis showed that elevated MGST1 expression was related to tumour development and poor prognosis, as well as dysregulated infiltration of immune cells in UCEC, which can be a potential prognostic indicator and ferroptosis‐based immunotherapy target." (PMID 35218676, 2022). "All these results indicate that the expression of MGST1 notably changes the tumour microenvironment by regulating the ferroptosis of immune cells." (PMID 35218676, 2022). "Mounting evidence has suggested that MGST1 exerts an inhibitory effect on ferroptosis in tumor cells, which might be a promising therapeutic target." (PMID 39850123, 2025).